PPP1R15B (protein phosphatase 1 regulatory subunit 15B)
Description:
Maintains low levels of EIF2S1 phosphorylation in unstressed cells by promoting its dephosphorylation by PP1.
Synonyms: FLJ14744; CREP; MSSGM2
Tractability: Small molecule: a structure with a bound ligand is known. PROTAC: ubiquitination databases record sites on it; a small molecule that binds it is known.
Target class: Protein phosphatase regulatory subunit; Phosphatase; Enzyme; Protein Phosphatase
Gene: Protein-coding gene on chromosome 1 (204,396,492 to 204,411,887, reverse strand). Ensembl gene ENSG00000158615.
Subcellular location (Human Protein Atlas): Golgi apparatus
Gene Ontology:
Molecular function: eukaryotic initiation factor eIF2 binding; molecular adaptor activity; protein binding; protein phosphatase 1 binding; protein phosphatase regulator activity
Biological process: negative regulation of protein phosphorylation; negative regulation of PERK-mediated unfolded protein response; response to endoplasmic reticulum stress; regulation of protein metabolic process
Cellular component: protein phosphatase type 1 complex; endoplasmic reticulum
Genetic constraint (gnomAD): Loss-of-function variants: 32 observed, 58.45 expected, observed/expected ratio (o/e) 0.55, 90% interval 0.41 to 0.74. The upper end of that interval is the gene's LOEUF score, 0.74, which puts it in group 3 of 6, group 1 being the genes least tolerant of losing a copy. Missense variants: 928 observed, 902.78 expected, observed/expected ratio (o/e) 1.03, 90% interval 0.97 to 1.09. Synonymous variants: 345 observed, 352.68 expected, observed/expected ratio (o/e) 0.98, 90% interval 0.89 to 1.07.
Homologues: Orthologues: chimpanzee PPP1R15B (99% identical), macaque PPP1R15B (93% identical), pig PPP1R15B (75% identical), guinea pig PPP1R15B (69% identical), mouse Ppp1r15b (67% identical), rat Ppp1r15b (67% identical), dog PPP1R15B (66% identical), Drosophila melanogaster PPP1R15 (10% identical). Paralogues in human: PPP1R15A (13% identical).
Diseases named in the same sentence as PPP1R15B in open-access papers:
PPP1R15B is named in the same sentence as 26 diseases in open-access papers, as found by Europe PMC text mining. Sharing a sentence is not in itself a finding about the gene and the disease. The quoted sentences say what the papers report.
diabetes (5 papers, 2023 to 2024). "To determine the effects of miR-98-5p-PPP1R15B interaction, we assessed the impact on another major hepatic hallmark during diabetes i.e. lipogenesis." (PMID 36917438, 2023). "Other established regulators of beta cell function and genes involved in monogenic diabetes or T2D risk were identified among the screening hits, such as NKX2.2, SLC2A2, PPP1R15B and IGF2 28–35." (PMID 36543916, 2023). "In this study we present evidence to show that miR-98-5p, whose levels are down-regulated in the circulation during diabetes, regulates hepatic gluconeogenesis and lipogenesis by targeting PPP1R15B." (PMID 36917438, 2023). "All these suggest that by targeting PPP1R15B, miR-98-5p regulates hepatic steatosis and glucose output; deregulation of which are characteristic hepatic features during diabetes." (PMID 36917438, 2023). "Here we show that miR-98-5p, that is down-regulated in the circulation during diabetes, regulates hepatic gluconeogenesis and lipogenesis by targeting PPP1R15B." (PMID 36917438, 2023). "To determine the consequent effects of miR-98-5p-PPP1R15B interaction mediated p-eIF2α accumulation, we assessed the impact on two evident aberrant hepatic hallmarks during diabetes: gluconeogenesis and lipogenesis." (PMID 36917438, 2023). "Therapeutic intervention of the miR-98/PPP1R15B axis might offer a potential strategy to target aberrant hepatic metabolism during diabetes." (PMID 36917438, 2023).
cervical cancer (1 paper, 2025). A primary or metastatic malignant neoplasm involving the cervix. "Using genome-wide analysis, we identified thousands of similar competition sites across the genome, many near cancer-related genes like PPP1R15B and LRRC37A, which are linked to poor survival in cervical cancer patients." (PMID 40953061, 2025). "High expression levels of either PPP1R15B or LRRC37A were correlated with poor survival outcomes in patients with cervical cancer." (PMID 40953061, 2025).
cancer (2 papers, 2023 to 2025). A tumor composed of atypical neoplastic, often pleomorphic cells that invade other tissues. "We validated competition at two CBSs in the promoter and found it likely regulates cancer-related genes PPP1R15B and LRRC37A." (PMID 40953061, 2025).
metabolic disease (1 paper, 2023). A congenital disorder (due to inherited enzyme abnormality) or acquired (due to failure of a metabolically important organ) disorder resulting from an abnormal metabolic process. "To conclude, our data identifies the miR-98-5p/PPP1R15B axis as a significant regulator of hepatic gluconeogenesis and lipogenesis and offers a possible path to explore the therapeutic potential of this axis to target deregulated hepatic metabolism during metabolic diseases." (PMID 36917438, 2023).
PPP1R15B also shares sentences with these, for which no sentence is quoted: microcephaly (4 papers); infection (2); intellectual disabilities (2); Obesity (2); anemia (1); autism (1); breast carcinoma (1); cardiac hypertrophy (1); colorectal cancer (1); endometrial cancer (1); gastric cancer (1); Hepatic steatosis (1); Insulin resistance (1); learning disability (1); liver cancer (1); lung carcinoma (1); maturity-onset diabetes of the young (1); neuroblastoma (1); pancreatic cancer (1); schizophrenia (1); Vanishing White Matter disease (1); viral infection (1).